KNDC1 (kinase non-catalytic C-lobe domain containing 1)
Description:
RAS-Guanine nucleotide exchange factor (GEF) that controls the negative regulation of neuronal dendrite growth by mediating a signaling pathway linking RAS and MAP2 (By similarity). May be involved in cellular senescence.
Synonyms: v-KIND; C10orf23; KIAA1768; RASGEF2; bB439H18.3; FLJ25027; Very-KIND
Tractability: Antibody: the Human Protein Atlas places it where antibodies can reach. PROTAC: its protein half-life has been measured.
Gene: Protein-coding gene on chromosome 10 (133,160,034 to 133,226,412, forward strand). Ensembl gene ENSG00000171798.
Subcellular location: Cell projection, dendrite; Perikaryon
Subcellular location (Human Protein Atlas): Cytosol; Plasma membrane; Vesicles
Gene Ontology:
Molecular function: guanyl-nucleotide exchange factor activity
Biological process: cerebellar granule cell differentiation; regulation of dendrite development; regulation of dendrite morphogenesis; small GTPase-mediated signal transduction
Cellular component: dendrite; guanyl-nucleotide exchange factor complex; neuronal cell body; perikaryon
Genetic constraint (gnomAD): Loss-of-function variants: 104 observed, 150.13 expected, observed/expected ratio (o/e) 0.69, 90% interval 0.59 to 0.81. The upper end of that interval is the gene's LOEUF score, 0.81, which puts it in group 3 of 6, group 1 being the genes least tolerant of losing a copy. Missense variants: 2,301 observed, 2,241.9 expected, observed/expected ratio (o/e) 1.03, 90% interval 0.99 to 1.06. Synonymous variants: 1,074 observed, 990.98 expected, observed/expected ratio (o/e) 1.08, 90% interval 1.03 to 1.14.
Homologues: Orthologues: chimpanzee KNDC1 (90% identical), mouse Kndc1 (77% identical), rat Kndc1 (77% identical), guinea pig KNDC1 (76% identical), dog KNDC1 (60% identical), rabbit KNDC1 (52% identical), tropical clawed frog kndc1 (43% identical).
Diseases named in the same sentence as KNDC1 in open-access papers:
KNDC1 is named in the same sentence as 9 diseases in open-access papers, as found by Europe PMC text mining. Sharing a sentence is not in itself a finding about the gene and the disease. The quoted sentences say what the papers report.
acute myeloid leukemia (1 paper, 2010). Acute myeloid leukemia (AML) is a group of neoplasms arising from precursor cells committed to the myeloid cell-line differentiation. "GPR123 and KNDC1 have recently been shown to be mutated in acute myeloid leukemia by using whole-genome sequencing methodology, whilst PRDM12 is located in a minimal commonly deleted region in chronic myeloid leukemia." (PMID 20184741, 2010).
COVID-19 (1 paper, 2022). A disease caused by infection with severe acute respiratory syndrome coronavirus 2. "Another two genes, KNDC1 and STK32C, adjacent genes for the same SNP rs148148613, tend to be expressed higher in most of GTEx tissues of females than males, and they are stimulated in blood of COVID-19 patients." (PMID 36353114, 2022).
ovarian carcinoma (1 paper, 2020). A malignant neoplasm originating from the surface ovarian epithelium. "For the two ovarian cancer samples, dpCNV gets 225 cytobands and 128 cytobands, 285 genes and 529 genes overlapped with the COSMIC database, respectively, in which there are many important tumor driver genes corresponding to ovarian cancer, such as PUM1, GOLPH3L, PIWIL4, and KNDC1." (PMID 33519925, 2020).
KNDC1 also shares sentences with these, for which no sentence is quoted: tumor (2 papers); chronic myeloid leukemia (1); glioma (1); hereditary optic neuropathy (1); neurodegenerative disease (1); ovarian insufficiency (1).